IFNG (interferon gamma)
Diseases named in the same sentence as IFNG in open-access papers (continued):
Sharing a sentence is not in itself a finding about the gene and the disease.
infection (continued). "Additionally, the ability to produce cytokines IFNγ, TNFα, and IL-2 was unaffected in aPKC-deficient CD8+ T lymphocytes at 50 days post-infection." (PMID 26765121, 2016). "What additional factor(s) might contribute to driving NK cell transitioning from IFNγ to IL-10 production during Listeria and other infections remains to be determined." (PMID 27295349, 2016). "The appearance of polyfunctional (IFNγ+CD107a+) cNK cells in a response to T. gondii parasites may be advantageous for the resolution of the infection." (PMID 27721814, 2016). "Widespread F4/80+ activated microglial staining was reported in MV-infected NSE-CD46+ pups at 7 dpi, leaving open the possibility that the effects we observed on NSPCs and immature neurons were due to indirect effects on IFNγ-responsive microglia during infection." (PMID 27178303, 2016). "Therefore, the elevated percentage of DN NKT cells in women suggests that production of protective IFNγ during infection will be higher in women than in men." (PMID 26895635, 2016). "We compared the expression profile of Th1 (IFNγ) and Th2-associated (IL-4 and IL-10) mRNAs in dLNs of WT and CatB-/- mice during infection since we found no detectable transcripts in the FPs." (PMID 27182703, 2016). "Furthermore, at an early time point of infection T cells from PbA-infected Il22−/− mice showed an enhanced IFNγ but a diminished IL-17 production." (PMID 27311945, 2016). "Together, these results suggest that IFNγ may provide important protection both early and late post infection." (PMID 28119902, 2016). "Moreover, it has been puzzling that an Lm expressed virulence protein, p60, promotes NK cell activation and IFNγ production during infection." (PMID 27295349, 2016). "In vitro and in vivo infection by the intracellular bacterium Francisella noatunensis gave a significantly reduced LygF1a and b expression but increased expression of the LygF1c and d genes as did also the interferon gamma (IFNγ) cytokine." (PMID 27324690, 2016). "During SchuS4 infection, serum levels of IL-6 and G-CSF were higher while IFNγ levels were reduced." (PMID 27015566, 2016). "As a mechanism of resistance by IFNγ to the infection, it is generally believed that after infection, activation of CD4+ T cells by mycobacterial antigens results in clonal expansion and the production of IFNγ, which activates macrophages resulting in their becoming mycobactericidal." (PMID 26999357, 2016). "Interestingly, mice inoculated with T. cruzi displayed elevated IL-18 levels 6 days after infection followed by an increase of IL-12 and IFNγ." (PMID 27027876, 2016). "To test this hypothesis, we have used an experimental BU mouse model and compared the disease progression in WT and IFNγ-/- mice during active infection with a highly virulent M. ulcerans strain recently isolated from the lesion of a BU patient." (PMID 26863011, 2016). "The CD4+ T cell response to the MCMV m09133-147 epitope (here referred to as m09) was described as inflationary with 0.11–0.21% of the peripheral CD4+ T cell population producing IFNγ in response to m09 stimulation in persistently infected animals (days 40–100 post-infection)." (PMID 27861512, 2016). "In mice consuming the WB-enriched diet, the expression of the Th17 cytokine, Il-17A was lower than mice consuming the RS-enriched and CN diets during peak infection, and by late infection, these mice exhibited the lowest expression of Th1 (Il-1β, Ifnγ, Tnfα) cytokines." (PMID 28031748, 2016). "Moreover, we show that the combined activity of interferon-gamma and interleukin-10 limits the magnitude of infection-induced Tfh responses, the secretion of parasite-specific secreted antibody, and parasite control." (PMID 27732671, 2016). "Defense against R. australis is largely mediated by the cytotoxic activity of CD8+ T cells rather than IFNγ as C57BL/6 Perforin-/- mice showed enhanced susceptibility to this infection compared to wild-type mice." (PMID 27875529, 2016).
infection (continued). "Surprisingly, 6 months after infection, several proinflammatory genes were downregulated in peripheral blood cells of H. felis-infected Plcg2Ali5/+ mice as compared to infected WT mice, including two important inflammatory cytokines, IFNγ and IL-1a." (PMID 26966907, 2016). "Although basal transcription of Ifnγ, S100A9 and Lcn2 was similar between mock-infected WT and mock-infected Ifnar1-/- mice, the transcription of Ifnγ and Lcn2 was significantly higher in the ceca of the Ifnar1-/- group, compared to the WT group, after infection with S. Typhimurium alone." (PMID 27149619, 2016). "Defining the anti-viral cytokine profile in CD46+ and CD46+/IFNγ-KO pups may provide insight into the milieu that is required to maintain the NSPC pool during infection." (PMID 27178303, 2016). "However, inverse changes in IFNα and IFNγ expression after AIV H9N2 strain infection were observed in vitro." (PMID 26925041, 2016). "Moreover, inoculation of log-phase parasites led to better activation of lymph node CD4+ T cells (IFNγ production) than inoculation of metacyclic promastigotes, at least during the early stages of infection (16 h and 3 days post-inoculation)." (PMID 26969511, 2016). "Interestingly, only the SLA-SE-induced rPmpD-specific IFNγ response was significantly boosted following Ct infection." (PMID 27389169, 2016). "CD28 is the classic positive co-stimulatory receptor that, acting in conjunction with the T cell receptor (TCR), induces T cells to undergo proliferation and to produce cytokines such as interferon gamma (IFN-γ) and interleukin-2 (IL-2) that are critical in controlling infection." (PMID 26786705, 2016). "At a time-point of infection in which T. borreli induced higher levels of IFNγ expression than induced by T. carassii, only T. carassii induced enhanced IL-17A/F expression, which was accompanied by a marked neutrophil infiltration into the spleen of only T. carassii-infected fish." (PMID 26593954, 2015). "To do this, we performed high throughput RNA-sequencing (RNA-seq) on BMDM obtained from the same 26 age- and sex-matched AXB/BXA mice described above and their progenitors (28 samples in total), before (resting, controls) and after infection with Toxoplasma or stimulation with IFNG+TNF, or CpG." (PMID 26510153, 2015). "In contrast, we noted an increase in a subset of Th17-associated cytokines in the BAL, specifically IL-17, IL-6, G-CSF, and CCL4, and elevated levels of these cytokines were sustained even after the majority of the IFNγ response had subsided, i.e. day 14 post infection." (PMID 25849970, 2015). "An indicator for such reactivation is the still increased level of IFNγ 148 days post infection." (PMID 25989070, 2015). "NK cells respond to sublethal doses of L. monocytogenes during the infection of rats by an induction of IFNγ in the spleen, whereas a lethal dosis of the same pathogen leads to excessive IFNγ production in mice, which impairs granulocyte migration to the spleen and reduces Listeria clearance." (PMID 26296209, 2015). "One of the most interesting findings of this study is the observation that fexofenadine treatment caused significant reductions in circulating IgE levels and splenocyte production of IL-5 and IFNγ as well as increased numbers of eosinophils at the site of infection." (PMID 26204515, 2015). "Moreover, IFNγ-induced effect on astrocyte infection was totally abrogated by the anti-TNF antibody Infliximab." (PMID 25695249, 2015). "Additionally, exposure of a human airway epithelial cell line (A549) to IFNγ for 48 h prior to RSV infection reduced 2-day post-infection viral titers when compared to IL-4 treated or control cells." (PMID 26438053, 2015). "We also demonstrated that knockdown of IRF1 could modestly rescue EBOV GP/rVSV infection in peritoneal macrophages that were stimulated with IFNγ." (PMID 26562011, 2015).
infection (continued). "As IRF1 is a transcription factor critical for IFNγ signaling by driving downstream expression of many IFNγ target genes, we also assessed if knock down of IRF1 in M-CSF-treated and M-CSF/IFNγ-treated macrophages altered infection of EBOV GP/rVSV in peritoneal macrophages." (PMID 26562011, 2015). "Similar to Yersinia, NK cell-mediated production of IFNγ was also observed during infections with other enteric pathogens, e.g. C. rodentium, S. enterica serovar Typhimurium and L. monocytogenes, but the outcome varied significantly among the bacterial infections." (PMID 26296209, 2015). "This was further substantiated by the observation that anti-IFNγ antibodies could prevent early mortality in these infections." (PMID 26566996, 2015). "Thus, as the concentration of IFNγ and TNFα increase during the latter time points of infection and clearance in WT mice, the concomitant increase of IL-4 and IL-6 appears to protect the mitochondrial functions of the colonic epithelium." (PMID 26481427, 2015). "Importantly, the dual signaling by IFNγ priming and T. cruzi infection, the condition that significantly increased infection rates and replication, also provided the conditions to trigger NO production by astrocytes." (PMID 25695249, 2015). "Elevated interferon gamma (IFNγ) and IL-1β also indicated infection-enhanced inflammation." (PMID 26619277, 2015). "Combining treatments of TNFα and IFNγ, in analogy with the in vivo cytokine expression during day 14 and 19 post infection, further decreased the intensity of the complex-I and IV staining, but this loss was alleviated by simultaneous treatment with IL-4 (P < 0.01 vs P < 0.001)." (PMID 26481427, 2015). "To determine whether this robust Th1 profile observed by transcript analysis in tissue was also observed systemically by protein analysis, we measured IL-12 and IFNγ cytokine levels in serum of mice at 4 weeks post-infection." (PMID 26252010, 2015). "Thus, we tested the participation of NO on IFNγ-pretreated induction of astrocyte infection by T. cruzi." (PMID 25695249, 2015). "Given our results following infection of CXCL9-depleted mice, we hypothesized that IFNγ-/- mice would be similarly susceptible to crypt penetration by C. rodentium due to the attendant decrease in CXCL9 expression." (PMID 25643352, 2015). "Therefore, we investigated the participation of IFNγ in astrocyte infection by T. cruzi and found that this cytokine promoted parasite uptake and growth in primary astrocyte cell cultures." (PMID 25695249, 2015). "Most of the IFNγ is produced by CD4+ T-cells at later stages of the infection." (PMID 26296209, 2015). "There is evidence that T. gondii infection promotes the production of factors, such as interferon-gamma (IFN-γ), that suppress immune privilege which has a crucial role in protecting against infection, as well as being a potent TGF-β antagonist and hyper-regulating the expression of MHC molecules." (PMID 26672749, 2015). "Chest X-rays and tuberculin skin test and/or an interferon-gamma release assay should be used to screen TNFi candidates for latent TB infection and prophylactic anti-TB therapy initiated in patients with a high suspicion of infection." (PMID 26793241, 2015). "We postulate that IFNγ may be augmenting mechanisms of viral resistance in airway epithelial cells that dramatically reduce the viral burden at the onset of infection." (PMID 26438053, 2015). "Further, NO played a role in IFNγ-induced infection of astrocytes by T. cruzi." (PMID 25695249, 2015). "MHV-68 infection strongly induced immunoproteasome expression: mRNA levels of all three immunoproteasome subunits were highest at day 14 post infection and declined to control levels after 148 days, even though IFNγ and TNFα transcript levels were still increased at that time point." (PMID 25989070, 2015).
infection (continued). "In these model systems effective immunity is dependent on robust CD4+ T-cell immune responses, the production of Th1-type cytokines such as interferon-γ (IFNγ), and “classical” activation of effector cells such as macrophages, leading to killing and clearance of infection." (PMID 25853653, 2015). "In contrast to the loss of staining intensity of subunits of complex I and IV found in colons from WT mice after infection, there was no statistically significant loss of any of the four complexes in IFNγ−/− mice." (PMID 26481427, 2015). "We further show that activation of AMs and pulmonary DCs are significantly enhanced upon delivery of intranasal IFNγ with expedited RSV clearance early in infection without eliciting weight loss commonly associated with the systemic delivery of IFNγ." (PMID 26438053, 2015). "Importantly, aggregated APECs induced by Ifnγ contain fewer intracellular S. Typhimurium compared to their single counterparts post infection." (PMID 26029930, 2015). "Furthermore, we demonstrated that interferon gamma profoundly inhibits Ebola virus infection of macrophages, an early cellular target of infection." (PMID 26562011, 2015). "IFNγ was highly effective at inhibiting infection by this recombinant virus." (PMID 26562011, 2015). "As previously shown, systemic IFNγ was present in quantifiable amounts at day 3 post infection." (PMID 26070118, 2015). "Interestingly, serum from infected Mir155-/- mice had very low IFNγ levels, compared to serum from the other three strains at 4 weeks post-infection, and infected Il10-/- mouse serum had very high IFNγ levels, compared to serum from the other three strains." (PMID 26252010, 2015). "Moreover, we did show a similar response from mammalian expressed endotoxin-free mS100A9 in vitro, and by adenovirus-mS100A9 infection in vivo, which resulted in the induction of IL-6 and IFNγ in a TLR4-dependent fashion." (PMID 25706559, 2015). "However, here, it has not been observed as a result of the massive introduction of IFNγ-producing T cells but simply as a result of T-cell stimulation in parallel to mimicking a local infection." (PMID 26337837, 2015). "In addition, we determined if human IFNγ inhibits EBOV GP/rVSV infection of an in vivo matured macrophage population, human alveolar macrophages." (PMID 26562011, 2015). "As the production of interferon-γ (IFNγ) and interleukin 17 (IL-17) by γδ T cells can influence the outcome of an immune response we analyzed the intracellular IFNγ and IL-17 production during infection in spleen, liver and lung of CD8-/-JHT mice by flow cytometry." (PMID 25658831, 2015). "Transcripts of IL-2 and IFNγ appear to be less abundant in the later stages of infection, which is consistent with the Th2-type response and concurrent suppression of Th1-type cytokine levels observed in the gastric lymph node during O. ostertagi infection of cattle." (PMID 24712712, 2014). "However, infection with T. cruzi outranged the elevated inos mRNA synthesis as compared to IFNγ stimulation of cells." (PMID 25340519, 2014). "This showed that at all times after infection <1% of cells were positive for IFNγ or IL-13." (PMID 25474738, 2014). "Furthermore, the kinetic analysis of IL-12 and IFNγ levels in the sera after infection shows that patient 2 promoted an early Th1 response mediated by IL-12 and IFNγ in response to MERS-CoV." (PMID 24551142, 2014). "The unambiguous conclusion from our experiments is that infection by E. cuniculi is resisted in IFNγ-induced mouse fibroblasts by the action of the IRG proteins, and several aspects of the process closely resemble features that have been studied in detail in T. gondii infection." (PMID 25356593, 2014). "The major immune response to infection by M. tuberculosis is focused on the type 1 helper T lymphocytes (Th1) capable of synthesizing interferon-gamma (IFN-γ) and other cytokines, which manage to contain M. tuberculosis in a latent state without active replication." (PMID 24803999, 2014).
infection (continued). "This likely reflects the impact of other cytokines, such as IFNγ, which may modulate the M2 phenotype during infection." (PMID 25144366, 2014). "However, it was recently suggested in a model of infection caused by vaccinia virus inoculation in C57BL/6 mice that F4/80+Ly6G+ cells are indeed monocytes with a great capacity of producing ROS and IFNγ whilst Ly6G− monocytes produce NO and TNFα." (PMID 25242870, 2014). "Serum IFNγ levels were significantly increased in INOC gilts early in infection." (PMID 25479904, 2014). "The observation that the in vivo IFNγ response was almost entirely CD1d-dependent suggests that our in vitro infection model may be over-estimating the effect of cytokine-driven stimulation." (PMID 24391492, 2014). "Following removal of IFNγ from the host cell, and subsequent resumption of tryptophan synthesis, these unique forms quickly differentiate back into infectious EBs and continue the infection." (PMID 25386180, 2014). "Given that lncRNA NeST is involved in inflammation during microbial infection and that IFNγ methylation increases with advancing age, NeST could contribute to the inflammatory response and infection in elderly." (PMID 25543668, 2014). "In contrast, the second infection included morphologically aberrant forms similar in ultrastructure to in vitro persistence induced by IFNγ, a high euo:omcB mRNA expression profile, low infectious titer, and large bacterial DNA load together with a local IFNγ response." (PMID 24918090, 2014). "In our study we confirm that, even in the absence of any exogenous IFNγ added to the cells, infection with the highly pathogenic Y strain of T. cruzi results in a robust increase in the amount of cellular STAT1." (PMID 25340519, 2014). "We also examined whether iNKT cells controlled Mtb growth through nitric oxide, an important mediator of antimycobacterial immunity produced during infection by IFNγ stimulation of the enzyme inducible nitric oxide synthase (iNOS)." (PMID 24391492, 2014). "These include IFNγ, sub-inhibitory concentrations of antibiotics, nutrient deprivation, co-infection with either herpes simplex virus or Toxoplasma gondii in vitro, and infection with Chlamydia-phage." (PMID 24959424, 2014). "Among other mechanisms, including killing by iNOS and IDO, the IFNγ-induced p47 GTPases have been placed at the centre of the initial defense against invading Toxoplasma gondii parasites, since shortly after infection they facilitate the disruption of the parasitophorous vacuole." (PMID 25340519, 2014). "Besides activating complement, they limit infection by stimulating the secretion of interferon gamma (IFN-γ), IL-17, IL-6, tumor necrosis factor alpha (TNF-α), and nitric oxide (NO) by macrophages." (PMID 25654073, 2014). "IFNγ plays an important role in M1 macrophage differentiation at infection sites." (PMID 24904837, 2014). "Importantly, the molecular and morphological analyses described here indicate that persistent growth forms can be isolated from the human endocervix when the infection microenvironment resembles the in vitro model of IFNγ-induced persistence." (PMID 24959423, 2014). "We must recall that IFNγ injection increases mortality in animal models of polymicrobial infection." (PMID 24886820, 2014). "However, in a model of infection with Mycobacterium tuberculosis, the IL-22 cells are dependent on IL-23 and the majority of the IL-22-producing T cells also express IFNγ." (PMID 25253467, 2014). "For example, even though IFNγ may promote phago-lysosomal fusion upon infection with the less virulent F. novicida, it does not appear to protect human MDM against Schu S4." (PMID 24600590, 2014). "Although signaling by IFNγ is crucial for control of Mtb, clinical data shows that IFNγ present at the site of ongoing infection is inadequate to clear bacteria and IFNγ levels produced by CD4+ T cells do not correlate with disease progression or protection provided by BCG vaccination." (PMID 24391492, 2014).